MPO (myeloperoxidase)
Diseases named in the same sentence as MPO in open-access papers (continued):
Sharing a sentence is not in itself a finding about the gene and the disease.
vasculitis (continued). "The combination of anti-histone antibody, MPO, and/or PR3 ANCA and absence of anti-dsDNA antibody could be used to support the diagnosis of hydralazine-induced vasculitis in the appropriate clinical setting with evidence of pauci-immune glomerulonephritis." (PMID 25210633, 2014). "Although there are no data on the capacity of MPO-ANCA to stimulate secretion of any cytokine, including MIF, we would expect it to be related to disease activity and MIF levels, because there appears to be positive relation between MPO-ANCA titers and vasculitis disease activity." (PMID 22046508, 2010).
Sepsis (278 papers, 2009 to 2026). Sepsis is defined as life-threatening organ dysfunction caused by a dysregulated host response to infection. "A significant factor in organ dysfunction in sepsis is the widespread activation of neutrophils, which is frequently associated with elevated MPO levels, leading to oxidative stress and tissue damage." (PMID 40772192, 2025). "In comparison to other biomarkers, cfDNA and MPO provide an additional diagnostic value to CRP for sepsis diagnosis." (PMID 40731775, 2025). "Although MPO-DNA was not identified as an independent risk factor, previous studies have suggested that MPO-DNA has certain prognostic value in sepsis and organ failure." (PMID 39457503, 2024). "Further analysis identified both as independent risk factors for NOAF in sepsis (MPO: OR: 1.74, 95% CI: 1.08–2.83; HOCl: OR: 1.04, 95% CI: 1.03–1.05)." (PMID 39030470, 2024). "In summary, our study indicates that the levels of MPO-DNA and cf-DNA are significantly elevated in sepsis patients and are associated with multi-organ damage and inflammation." (PMID 39457503, 2024). "Previous studies have shown that sepsis can cause neutrophils to form NETs and release a large amount of MPO, DNA and other active substances." (PMID 36721229, 2023). "MPO is associated with increased mortality in patients with sepsis and a recent study demonstrated that GAS NSTIs patients had higher MPO levels in blood serum as compared to polymicrobial NSTIs." (PMID 37430325, 2023). "Noteworthy, specific components of NETs, such as circulating levels of cfDNA, neutrophil elastase, and the myeloperoxidase–DNA complex in patients with sepsis, are positively correlated with the risk of VTE." (PMID 37081895, 2023). "Significantly higher levels of NETs, indicated by coexpression of CitH3 and MPO in blood, were observed in humans with sepsis-associated ARDS, and enhanced CitH3-NE coexpression was observed in mouse lung tissue." (PMID 35637949, 2022). "The positive correlation of the serum cfDNA and MPO-DNA levels with IL-8 levels further supports the role of enhanced NETosis levels in the development of sepsis-associated lung injury and is associated with diagnosis severity." (PMID 35637949, 2022). "By contrast, reduced neutrophil MPO expression has been suggested as being a good predictor of a higher risk of mortality in patients with sepsis." (PMID 36421487, 2022). "Plasma concentrations of heparin-binding protein (HBP), myeloperoxidase (MPO), IL-6 and IL-8 appear to be correlated with emergence of the first sepsis-associated organ dysfunction." (PMID 34945111, 2021). "Sepsis also caused significant increases in tissue MPO content (an indicator of neutrophil leukocyte infiltration) in both hippocampal and cerebellar tissues." (PMID 34475875, 2021). "A molecular footprint of MPO are proteins containing chlorinated tyrosine (Cl-Tyr), which along with an additional MPO halogenation product 3-bromotyrosine, were reduced in MPO-deficient mice with sepsis." (PMID 33569056, 2020). "‘Secondary’ MPO deficiency has been correlated with neutrophilic consumptive conditions, such as sepsis, and other overwhelming infections, such as parvovirus, pneumonia, and pancreatic abscesses." (PMID 32442236, 2020). "The MPO rs2333227 polymorphism was previously associated with more frequent sepsis in a cohort of SCA children, thus suggesting a deleterious effect." (PMID 32937882, 2020). "MPO-deficient mice have been reported to show increased mortality in a polymicrobial sepsis model, and more recently, blockade or genetic deletion of MPO has been reported to significantly increase mortality after LPS challenge." (PMID 31663003, 2019). "Third, a high plasma MPO-DNA levels on days 3 and 7 of sepsis were associated with 28-day mortality." (PMID 30005596, 2018).
Sepsis (continued). "At enrollment, sepsis was associated with significant increases in the expression of mRNAs related to redox metabolism (myeloperoxidase, 64-fold; PRDX3, 2.6-fold; SOD2, 2.2-fold) and redox-responsive genes (FOXM1, 21-fold; SELS, 16-fold; GLRX2, 3.4-fold)." (PMID 29540208, 2018). "Sepsis caused high levels of pulmonary myeloperoxidase, elastase, IL6, KC, liver myeloperoxidase, and capillary plugging." (PMID 28789683, 2017). "CLP-induced sepsis was associated with elevated MPO activity in both liver and lung of WT mice compared to sham-operated control mice." (PMID 27518439, 2016). "Sepsis-mediated lung injury was associated with a significantly higher number of infiltrating neutrophils, represented by the number of MPO positive cells in the septic animals when compared to shams (P<0.0001)." (PMID 24830455, 2014). "Enzymes, such as xanthine oxidase, phagocyte NADPH oxidase and MPO, have also been implicated in the overproduction of reactive oxygen species in sepsis and endotoxemia." (PMID 24691127, 2014). "Increased MPO association with neutrophil membrane was detected in blood from patients with inflammatory diseases, including sepsis, ischemia-reperfusion, or acute coronary syndromes compared with healthy controls." (PMID 23508943, 2013). "Furthermore, in an acute polymicrobial sepsis mouse model, Anxa2 deficiency increased myeloperoxidase (MPO) level and bacterial loads in renal tissues resulting in more severe renal damage." (PMID 37955107, 2023). "IL-17A-mediated neutrophil infiltration in the CNS may endanger neuronal cells by releasing oxidants through the activity of iNOS and MPO, thus promoting sepsis-associated CNS dysfunction." (PMID 37175808, 2023). "NETs control fungi but also promote vascular pathology during sepsis, suggesting that MPO could play beneficial or pathogenic roles during systemic challenge." (PMID 35945238, 2022). "Next, we investigated whether P2Y12 or P2Y1 antagonism alters sepsis-induced MPO activity similarly to receptor deficiency." (PMID 36405709, 2022). "Here we studied the kinetics of systemic neutrophil activation (HBP and MPO) and pro-inflammatory reaction (IL-6 and IL-8) in early sepsis in critically ill patients, using the emergence of the first sepsis-associated OD as a surrogate for the sepsis phase." (PMID 33461369, 2021). "Our study, which pinpointed ELANE and MPO as important DEGs, may provide insights into targeting neutrophils for the treatment of sepsis to prevent the collateral damage to peripheral organs caused by sepsis." (PMID 31817302, 2019). "A high MPO-DNA level on days 3 and 7 of sepsis was associated with 28-day mortality." (PMID 30005596, 2018). "When given subcutaneously 30 minutes before CLP, the TRPV1 capsazepine treatment significantly attenuated systemic inflammation and multiple organ damage caused by sepsis, as characterized by lowered lung and liver MPO activities and histological evidence of diminished pulmonary and hepatic injury." (PMID 24278674, 2012). "Further studies are required to investigate whether MPO deficiency could affect the lifespan of emigrated or circulating neutrophils, and whether changes in neutrophil longevity could contribute to protection against lung injury in this model of sepsis." (PMID 23508943, 2013). "Within the sepsis group, MPO-DNA and NE-DNA at day 3 strongly correlated with the immature-to-total neutrophil ratio (ρ = 0.76 and 0.72), suggesting these markers reflect neutrophil degranulation rather than NET formation." (PMID 42196477, 2026). "Functionally, the SYK inhibitor R406 suppressed changes in neutrophil features of activation from normal-density neutrophils and LDNs, including the SYK+ and SYK- neutrophil subsets, and MPO release from LDNs following LPS stimulation of sepsis neutrophils." (PMID 42012886, 2026).
Sepsis (continued). "We observed that in patients with sepsis, low-density neutrophils (LDNs) are elevated and phenotypically diverse populations of innate immune cells with varying degrees of maturity and myeloperoxidase expression." (PMID 42012886, 2026). "In the bone marrow biopsies there was no clear demonstration of increased amount of neutrophils, their precursors or the amount of MPO or NE-positive cells due to induction of sepsis." (PMID 39904820, 2025). "Considering strong evidence for the involvement of NETs—particularly CIT-HIST-H3 and MPO—in sepsis, our research aims to investigate their potential as diagnostic, prognostic, and therapeutic indicators in patients with sepsis in Critical care units." (PMID 41476244, 2025). "Gene expression profiling has identified several NET-related genes—ELANE, TLR4, MPO, PADI4, CTSG, MMP9, and S100A12—as being potential diagnostic biomarkers and therapeutic targets for sepsis." (PMID 40806591, 2025). "Although NETs are essential for pathogen clearance, their dysregulated formation-marked by excessive MPO, ROS, and cytotoxic chromatin release-has emerged as a double-edged sword, driving tissue damage and immune dysfunction in sepsis, autoimmunity and cancer." (PMID 41583494, 2025). "The increase in liver enzyme ALT and oxidative stress markers MDA and MPO confirmed sepsis‐induced liver injury." (PMID 39444093, 2025). "Neutrophil extracellular traps are composed of neutrophil-derived cfDNA and seem to be the most sensitive sepsis biomarker but rather specific compared to histones, such as citH3, and neutrophil cytoplasm-derived proteins such as MPO." (PMID 40731775, 2025). "This prompted us to evaluate MPO’s predictive value for 7-day mortality in our cohort, revealing it to be a strong predictor of sepsis-related death, with a cutoff of 84.9 ng/mL, sensitivity of 91.67%, and specificity of 91.23%." (PMID 41476244, 2025). "We also found a strong correlation between higher MPO levels and older patients with sepsis, as well as elevated bilirubin and creatinine levels." (PMID 41476244, 2025). "D+Q significantly reduced the oxidative stress caused by sepsis and improved liver function as evidenced by the diminished levels of liver ALT, MDA, and MPO." (PMID 39444093, 2025). "The role of neutrophil activation in sepsis—particularly the release of NETs that stimulate the production of ROS and MPO—has been emphasized in numerous studies." (PMID 41476244, 2025). "Our research focused on a consecutive follow-up over seven days post-MPO assay as a predictor tool, specifically evaluating short-term mortality rates in sepsis patients." (PMID 41476244, 2025). "Our study also highlighted a notable association between elevated levels of MPO and CIT-HIST-H3 in sepsis patients and several indicators, including high N/L ratios, increased JAAM scores used to diagnose DIC, and low serum fibrinogen levels." (PMID 41476244, 2025). "The correlation between MPO activity and histological changes highlights the potential of combined therapy for MSCs and SeNPs to attenuate sepsis-induced liver damage, underscoring the relevance of our findings." (PMID 40977719, 2025). "Similar results were obtained in the peripheral blood of mice in the LPS‐induced sepsis model, with elevated levels of CitH3‐DNA and MPO‐DNA complexes." (PMID 40586264, 2025). "This study investigates the impact of NETs biomarkers, specifically MPO and HIST, on the mechanisms underlying sepsis and sepsis-induced coagulopathy." (PMID 41476244, 2025). "The results showed that, compared to the Sham group, the number of MPO and CitH3 positive cells and their fluorescence intensities significantly increased in the sepsis group." (PMID 40779122, 2025). "MPO-DNA is a recognized marker of NET activation and has been associated with the 28-day mortality in patients with sepsis-induced AKI, similarly to the NE-DNA complex evaluated in the same study." (PMID 40806591, 2025).
Sepsis (continued). "By revealing a causal link between sepsis and CFHR5, FCER2, GZMB, HLA-DQA2, MBL2, or MPO, our study offers an essential resource for additional investigations on the subject." (PMID 39252215, 2024). "The results indicated that Neu (%), PCT, CRP, SAA, MPO-DNA, and cf-DNA were significant influencing factors for sepsis (p < 0.05)." (PMID 39457503, 2024). "This study aims to explore the clinical value of myeloperoxidase-DNA (MPO-DNA) and cell-free DNA (cf-DNA) in sepsis patients." (PMID 39457503, 2024). "We found that contents of MDA and MPO in the sepsis + saline group were significantly higher than the sepsis + remazolam group, suggesting that remazolam reduces the degree of lipid peroxidation and production of oxygen free radicals." (PMID 38646480, 2024). "MBL2 (odds ratio [OR] = 1.046) was a risk factor for sepsis, while the other proteins (FCER2: OR = 0.922; GZMB: OR = 0.908; CFHR5: OR = 0.858; HLA-DQA2: OR = 0.896; MPO: OR = 0.875) were safety factors." (PMID 39252215, 2024). "Consistent with our previous study, sepsis patients showed increased levels of dsDNA and MPO-DNA complexes." (PMID 38308264, 2024). "We developed a nomogram model to predict the incidence of NOAF during sepsis, incorporating MPO, HOCl, TNF-α, WBC, and APACHE II score." (PMID 39030470, 2024). "Compared with the sham operation + saline and sham operation + remazolam groups, the levels of MDP and MPO were significantly higher in the sepsis + saline group, while ATP level was lower, and the opposite was true in the sepsis + remazolam group." (PMID 38646480, 2024). "In this study, we constructed a predictive model for NOAF in sepsis using MPO and HOCl combined with TNF-α, WBC, and APACHE II score, which demonstrated a better predictive value with an AUC of 0.897." (PMID 39030470, 2024). "A study demonstrated that folic acid protects BBB permeability, decreases neuroinflammation by reducing MPO activity, and decreases oxidative damage to lipids in brain structures acutely after sepsis induction." (PMID 39183983, 2024). "Levels of dsDNA and myeloperoxidase (MPO) complexes were prominently elevated in patients with sepsis compared with those in individuals acting as healthy controls." (PMID 38888975, 2024). "The levels of MPO-DNA and cf-DNA are associated with the SOFA scores and PCT levels in sepsis patients." (PMID 39457503, 2024). "MPO activity levels were also significantly reduced at 0-6 hours post sepsis induction with UC-MSC treatment." (PMID 38381583, 2024). "Increased levels of LPO and MPO activity as well as decreased GSH levels were observed in the lung tissue of CLP-induced sepsis rats." (PMID 38911247, 2024). "Our unpublished studies have shown that during sepsis, neutrophils infiltrate the atrium and secrete more MPO." (PMID 39030470, 2024). "In sepsis patients, MPO-DNA and cf-DNA levels correlated with inflammation, coagulation, and organ damage indicators, as well as procalcitonin (PCT) levels and SOFA scores." (PMID 39457503, 2024). "To explore the relationship between MPO-DNA levels and PCT, we divided sepsis patients into MPO-DNA low-level group M1 (<2.25) and high-level group M2 (>2.25) based on the average MPO-DNA level of the sepsis patients." (PMID 39457503, 2024). "The data show that the CLP group experienced a marked increase in MPO levels compared to the control group, indicating a substantial elevation of oxidative stress due to sepsis (p < 0.001)." (PMID 38326366, 2024). "The study aims to preliminarily investigate the relationship between MPO-DNA, cf-DNA and the severity of sepsis, as well as their potential role in disease diagnosis." (PMID 39457503, 2024). "Consistent with this, a clinical study also demonstrated that cf-DNA levels are directly related to multiple organ dysfunction scores, sepsis-related organ function assessment, white blood cell count, and MPO levels." (PMID 39457503, 2024).